TET1 (tet methylcytosine dioxygenase 1)
Diseases named in the same sentence as TET1 in open-access papers (continued):
Sharing a sentence is not in itself a finding about the gene and the disease.
cancer (continued). "Numerous studies have demonstrated the participation of TET1 in the pathogenesis of cancers, and most of the researches are in keeping with our results." (PMID 34926132, 2021). "In another study that supports the oncogenic role of TET1, it was shown that TET1-mediated hypomethylation upregulated gene expressions that drove self-renewal and expansion of cancer stem cells in TNBC." (PMID 34209564, 2021). "We found that exogenously expressed TET1 protein significantly reduced the enhanced cancer cell invasion mediated by sh-circMEMO1 or miR-106b-5p overexpression." (PMID 33985545, 2021). "Epigenetic modification of DKK1 has been proved to act on Wnt/β-catenin signaling pathway, such as DNA demethylation mediated by TET1 during development and progression of cancer." (PMID 34863303, 2021). "Ectopic TET1 protein expression significantly reduced the enhanced cancer cell invasion and mesenchymal component expression and increased the weakened E-cadherin expression and global 5hmC level induced by sh-circMEMO1 or miR-106b-5p." (PMID 33985545, 2021). "These TET1-mediated hypomethylated sites were also enriched in cancer related pathways including but not limited to PI3K/mTOR pathway, Hippo signaling and others." (PMID 34209564, 2021). "The most important thing is that the reduction of TET1 expression appears to be a tumor suppressor gene that can promote the growth and metastasis of cancer." (PMID 32375881, 2020). "The dysregulated TET1 protein and 5 hmC level were reported to either suppress or promote carcinogenesis in a cancer type-dependent manner." (PMID 32528872, 2020). "The DNA hydroxymethylase TET1 has been reported to be transcriptionally activated by HIF-1α in cancer cells." (PMID 31935962, 2020). "In a word, the diversified role of TET1 seems to function in a cancer type-dependent or cell content-dependent manner." (PMID 32528872, 2020). "The cancer cells with TET1 knockdown showed lower levels of 5hmC, contributing to aberrant DNA methylation patterns in PTC." (PMID 32089682, 2020). "This experiment quantified the mediation of the TET1 survival effect through eight cancer hallmarks: apoptosis, cell cycle, cell death, cell motility, DNA repair, immune response, two phosphorylation pathways, and a randomized gene sets." (PMID 32483272, 2020). "The altered expression of the demethylation enzyme ten-eleven translocation (TET1) disrupts this balance, leading to aberrant DNA methylation patterns, which is seen in many human diseases, such as cancer." (PMID 32983650, 2020). "We further investigated the alteration frequency of TET1 across multiple cancer types with genomic data collected from cBioportal." (PMID 31623662, 2019). "TET1-MUT was strongly associated with higher ORR, better DCB, longer PFS, and improved OS in patients receiving ICI treatment, suggesting that TET1-MUT is a novel predictive biomarker for immune checkpoint blockade across multiple cancer types." (PMID 31623662, 2019). "With the exception of aberrant expression in cancer progression, TET1 is involved in cell differentiation." (PMID 31399111, 2019). "Previous studies have reported that several genes are directly targeted by miR-191 in human cancers including TET1, TIMP3, SATB1, and DIECR1." (PMID 31153371, 2019). "The expression of TET1 was under the negative regulation of miRNAs in cancer cells, such as miR-29, miR-26a, miR-767, miR-494 and miR-520b38." (PMID 31882783, 2019). "Considering the vital role of TET1-induced DNA demethylation in the progression of cancers, our results unraveled the therapeutic importance of circTRIM33–12 in HCC for the first time." (PMID 31153371, 2019). "The average alteration frequency of TET1 was 2.4% among these 39 cancer types, 22 of which had an alteration frequency above 1%." (PMID 31623662, 2019).
cancer (continued). "TET1 mRNA expression was significantly reduced in all BRAFV600E compared to BRAFWT or KRASG12V cancer cells or normal colon epithelial cells (CCD841CoN), and this downregulation was correlated with increased DNA methylation in the TET1 promoter." (PMID 31842975, 2019). "Like other cancer, the expression of TET1 is also reduced in cervical cancer, implying, an inherent role of TET activity in maintaining the hypermethylated status of target genes, and consequently, silencing of target genes." (PMID 31426393, 2019). "Taken together, our data indicate an important role for TET1 in cancer development and that TET1 represents a potentially novel biomarker in cancer therapy." (PMID 30988069, 2019). "Coversely, TET1 overexpression reverses the epithelial-mesenchymal transition and inhibits cancer cell metastasis by potent inhibition of canonical Wnt/β-catenin signaling." (PMID 30551127, 2018). "In contrast, overexpression of the short TET1 isoform in cancer cells had less effect on DNA methylation and gene expression than did the longer full-length form, and different genes were targeted." (PMID 29556496, 2018). "H&E staining showed normal epithelial and cancer cell morphology and IHC staining showed that both TET1 and 5hmC expression were higher in 3 normal septum deviation than in 33 NPC tissues." (PMID 30075814, 2018). "TET1 has been shown to be overexpressed and downregulated in different cancers and lymphoma patients compared to normal healthy controls." (PMID 29100411, 2017). "We found the expression levels of endogenous TET1 showed a significant positive correlation with the responsiveness of cancer cells across the NCI-60 panel to 953 compounds (r > 0.2; P < 0.05)." (PMID 29235481, 2017). "This indicates potential oncogenic role of TET1 in many cancers where TET1 expression level is relatively high." (PMID 29235481, 2017). "These mechanistic insights into reversible TSG hypermethylation in a pathway frequently altered in human cancer suggest a strategy for rational antagonism of miR-29b in tumors marked by high levels of miR-29b and low levels of TET1." (PMID 29088821, 2017). "In a recently published review of TET1 functions in cancer, the authors came to conclusion that this protein has a dual role in tumorigenesis." (PMID 28228863, 2017). "Direct knockdown of TET expression in fetal human colon epithelial cells with shRNA or re-expression in colon cancer cell lines were employed to determine that downmodulation of TET1 expression is required for cancer cell growth both in vitro and in vivo." (PMID 28587163, 2017). "Ten-eleven translocation methylcytosine dioxygenase 1 (TET1), an enzyme converting 5-methylcytosine (5-mC) to 5-hydroxymethylcytosine (5-hmC), is transcriptionally activated by hypoxia in cancer cells." (PMID 28808304, 2017). "We examined the epigenetic and genetic alterations of TET1 through analyzing cancer methylomes previously established by us31 and also online genomics database of common tumors." (PMID 27225590, 2016). "Levels of TET1 expression were similar between cancer tissues (median: 0.019; mean: 0.022; SD: 0.02) and normal mucosa (median: 0.015; mean: 0.018; SD: 0.01; P = 0.23)." (PMID 26093090, 2015). "In contrast, it is likely that Tet1/2/3 proteins are pre-activated in certain cancer-related settings leading to the preferential oxidation of 5mC to 5fC/5caC instead of 5hmC." (PMID 26300993, 2015). "Consistent with our findings, other reports have also indicated the relevance of TET1 promoter DNA methylation in cancer." (PMID 25557833, 2015). "In summary, TET1, TET2, and TET3 are required for maintenance of 5hmC at genes susceptible to hypermethylation in cancer." (PMID 24958354, 2014). "TET1 partly suppresses invasion in cancer by binding to TIMP2/3 and demethylating the promoters to activate TIMP2/3, and in turn down-regulates MMP expression." (PMID 24363660, 2013). "In contrast, other studies have defined TET1 as a cancer suppressor." (PMID 40599235, 2025).
cancer (continued). "Upregulated TET1 acts as an oncogene, leading to the hypomethylation and activation of cancer‐specific oncogenic signaling pathways (including phosphoinositide 3‐kinase [PI3K], epidermal growth factor receptor [EGFR], and platelet‐derived growth factor), which results in the development of TNBC." (PMID 40599235, 2025). "Interestingly, these results contrast with cancer biology, where TET1 often promotes migration and invasion." (PMID 41165593, 2025). "This elucidation effectively addresses the heterogeneity of the roles of TET1 in different cancers." (PMID 40599235, 2025). "To support the rationale of our hypothesis, we stratified public datasets to find the correlation between pGSN and TET1 and we identified positive correlation between pGSN and TET1 in multiple human cancer." (PMID 38216951, 2024). "Thus, the interaction between LINC01089 and TET1 plays a crucial role in regulating cancer progression." (PMID 39334363, 2024). "Despite the negative correlation between TET family genes expression and methylation levels in pan-cancer, unique patterns were observed, such as high methylation of TET1 in most analyzed cancers (except LIHC) and low methylation of TET2 and TET3 in most tumors." (PMID 39104395, 2024). "Increasing evidence indicates that TET1 is involved in the epigenetic regulation of proliferation and differentiation in various cells such as embryonic stem cells (ESCs), adult neural progenitor cells, muscle progenitor cells, and cancer cells." (PMID 38271970, 2024). "Notably, recent work has shown that RNA-m6A regulates TET-1-mediated DNA 5 hmC to promote transcription and chromatin accessibility in cancer." (PMID 38780787, 2024). "Also, a number of studies have highlighted TET1’s role as a promising target to overcome chemoresistance in different cancers." (PMID 38216951, 2024). "TET1 is known to promote DNA demethylation, which influences gene transcription, especially the genes related to proliferation and differentiation in ESCs, muscle progenitor cells and cancer cells." (PMID 38271970, 2024). "TET1 potently inhibited canonical Wnt/β‐catenin signalling by demethylating and upregulating two upstream antagonists of this pathway, SFRP2 and DKK1, which was associated with inhibition of EMT and cancer cell metastasis." (PMID 37994489, 2024). "TET1, a DNA demethylase, maintains genomic methylation homeostasis and accomplishes epigenetic regulation, which affect stem cells, immune responses and various malignant tumors." (PMID 38044421, 2023). "Moreover, TET1 acts in human cancers in both 5-hmC-dependent and -independent manners and the distribution of 5-hmC is inconsistent with the change in TET1-induced expression profile." (PMID 37020036, 2023). "Recent research has shown that TET1 can inhibit tumorigenesis and cancer progression." (PMID 35805009, 2022). "Our RNA sequencing analysis shows that knocking-down TET1 activates a variety of signaling pathways, of which the Wnt/β-catenin signaling pathway stood out due to its most significant changes and its widely studied roles in cancer initiation and progression." (PMID 35805009, 2022). "Also, TET1 was shown to inhibit cancer invasion and metastasis and correlates with better survival (Cell Reports 2, 568–579, September 27, 2012)." (PMID 35646706, 2022). "To unveil the molecular mechanisms of how TET1 may inhibit the expansion of cancer stem cells and EMT, we performed RNA-seq analysis of shTET1 cells (see declarations for dataset IDs)." (PMID 35805009, 2022). "In contrast, in PCa, where the basal cell layer was often destroyed, we could frequently detect TET1 expression in AMACR-positive cancer cells." (PMID 34844636, 2021). "Furthermore, treatment with DNMT inhibitor 5-aza-dC with or without histone deacetylase (HDAC) inhibitor, reversed the promoter methylation and repression of TET1 in cancer cell lines." (PMID 34209564, 2021).
cancer (continued). "Interestingly this anti-correlation between TET1 and immune regulators was also shown in other cancer types such as melanoma and lung and thyroid cancers." (PMID 34209564, 2021). "Being a potent anticancer agent, fisetin administration in in vitro and in vivo studies in kidney renal stem cells (HuRCSCs) effectively inhibited cancer cell stages such as proliferation, cell division, and invasion as well as lowered the TET1 expression levels." (PMID 33473265, 2021). "Similarly, Ruan and colleagues found that, of the 140 pairs of sample tissue, 95 (68%) exhibited lower levels of TET1 mRNA in cancer tissues as compared with their normal-tissue control counterparts." (PMID 34885145, 2021). "Interestingly, it was also reported that hypoxia-induced TET1 was associated with lipid metabolism in inducing EMT and cancer metastasis." (PMID 34957093, 2021). "We also determined that TET1, known to suppress various cancers, might be a useful biomarker for differential diagnosis of malignant and premalignant endometrial lesions, and it appears to be a significant prognostic factor for patients with EC." (PMID 34731191, 2021). "In patients treated with ICI, TET1-MUT was strongly associated with higher ORR, better DCB, longer PFS and improved OS, suggesting that TET1-MUT is a novel predictive biomarker for immune checkpoint blockade against multiple cancer types." (PMID 34656178, 2021). "Amount of studies suggest that 5hmC and TET1 play significant roles in cancer process." (PMID 34926132, 2021). "Their work establishes TET1 as a potential oncogene that contributes to aberrant hypomethylation in cancer and suggests that TET1 could serve as a druggable target for therapeutic intervention." (PMID 34656178, 2021). "Loss of TET1 induces EMT and metastasis in many kinds of cancer." (PMID 33953349, 2021). "It has been verified that high TET1 expression is associated with low levels of immune and defense response markers indicating that the prognostic value of TET1 expression in cancer might be related to the immune status of tumors." (PMID 33195409, 2020). "Taking together, dCas9-Dnmt3a/Tet1 could be an appropriate tool for implementing the new therapeutic strategies for UM and other cancer types." (PMID 32726977, 2020). "HIF1α is a transcription factor that has been shown to induce TET1 transcription in cancer cells." (PMID 31935962, 2020). "However, in some other cancers such as ovarian and triple-negative breast cancer, TET1 can promote carcinogenesis." (PMID 32528872, 2020). "The mediated effect measurement examines whether the TET1 effect on survival is mediated by one or more of the cancer hallmarks." (PMID 32483272, 2020). "TET1 is an important regulator of both cancer stemness and the EMT." (PMID 32799866, 2020). "Interestingly, the inverse interaction between immune signaling pathways and epigenetic regulation in cancer has also been observed, where NF-kβ interacts with TET1 promoter for its downregulation in breast cancer cells." (PMID 31968651, 2020). "In GC, TET1 has been identified as a crucial modulator in both tumorigensis and cancer progression." (PMID 33088215, 2020). "Moreover, modern technologies such as dCas9-Dnmt3a/Tet1 system have the potential to start a new era in the treatment of UM and other cancers." (PMID 32726977, 2020). "The next series of experiments investigated whether the TET1 effect on survival was mediated by sets of genes termed cancer hallmarks." (PMID 32483272, 2020). "The role of TET1 in gastric, breast, hepatic, prostate, and colon cancer is well-studied." (PMID 31399111, 2019). "TET1 downregulation has been shown to promote cancer invasion and metastasis." (PMID 31057717, 2019). "Moreover, TET1-catalyzed enrichment of 5hmC is required for overexpression of genes participating in cancer-related pathways and neuronal functions." (PMID 31311166, 2019). "Thus, it is also possible that Vc kills cancer cells by increasing the ability of TET1 to induce DNA demethylation." (PMID 30774978, 2019).
cancer (continued). "TET1 is involved in the growth, apoptosis, and cell cycle of cancer cells." (PMID 30988069, 2019). "Together, TET1 regulated 5hmC levels and may play a crucial role in the biological processes of cancer cells." (PMID 30988069, 2019). "Therefore, TET1-MUT can act as a novel predictive biomarker for immune checkpoint blockade across multiple cancer types." (PMID 31623662, 2019). "These lines of evidence suggest that GSNOR might be epigenetically downregulated in aggressive cancer as a consequence of Tet1 reduction, thus providing a new link between epigenetics and redox signaling." (PMID 30234010, 2018). "In addition, decreased expression of TET1 and TET2 and changes in the level of 5-hmC are thought to be associated with the onset and progression of several types of cancer." (PMID 28808304, 2017). "Ideally, this transcriptomic analysis should include mRNAs and miRNAs so that one can see ETS-1 and miR-29b increased with TET1 decreased as a subtype of cancer that could be opposed by miR-29b antagonism." (PMID 29088821, 2017). "While TET1 mutation is responsible for AML, the other TET2 and TET3 enzymes as well as TET enzyme cofactors (isocitrate dehydrogenases, IDH-1, and -2) were found mutated in several types of cancer and contribute to DNA methylation deregulation." (PMID 28587163, 2017). "Moreover, TET1 was increased by ROS resulting from 5-FU followed by induction of cancer drug resistance in CRC." (PMID 27183914, 2016). "Furthermore, the results also demonstrated that hypoxia-induced TET1/TET3 proteins made a great contribution to the activation of the TNFα- p38-MAPK pathway in regulating cancer stemness." (PMID 26869355, 2016). "Moreover, several reports demonstrated that hypoxia would enhance TET1 expression and lead to global DNA hypomethylation in different type of cancer." (PMID 26869355, 2016). "Here we show that TET1 can also function as a transcriptional repressor (of a miRNA) in cancer." (PMID 27116251, 2016). "Another study confirmed TET1 was involved in cancer cells proliferation via WNT signal pathway." (PMID 27183914, 2016). "The epigenetic mark 5-hydroxymethylcytosine (5hmC) is reduced in various cancers, and this may involve reduced expression of the ten-eleven translocation 1 (TET1) enzyme." (PMID 26973719, 2016). "The reports on the roles of TET1 in human cancers are increasing recently." (PMID 27121319, 2016). "Based on this finding, we suggest that TET1 in GCs may be one gene in a cluster in which the 3′-shore is methylated in a cancer-specific pattern." (PMID 26462176, 2015). "Although a decrease in 5hmC level in TET1 is associated with its LOE in various cancers including GC, the mechanism by which TET1 is suppressed in solid tumors has not been elucidated." (PMID 26462176, 2015). "Another hypothesis explaining the differences may be the infiltration of the so-called cancer stem cells with an embryonic pattern, which might be responsible for differences seen in TET1 expression." (PMID 26366235, 2015). "Thus, our data indicate that the 3′-shore of TET1 is a critical region for cancer-specific methylation for transcriptional regulation in primary GTs as well as GC cell lines." (PMID 26462176, 2015). "In conclusion, this work shows that PARP activity is a transcriptional regulator of TET1 gene through the control of epigenetic events and it suggests that deregulation of these mechanisms could account for TET1 repression in cancer." (PMID 24939750, 2014). "Notably, TET1 participates in the regulation of hypoxia and promotes cancer development." (PMID 40599235, 2025). "Mutations in TET1 or TET2 have been proposed to lead to widespread epigenetic alterations; however, it remains uncertain whether these mutations alone are sufficient to establish a cancer-specific epigenetic signature." (PMID 40663150, 2025). "Notably, while the loss of TET1 does not affect cell proliferation, it significantly inhibits cell migration, which is a crucial aspect of cancer progression." (PMID 40520993, 2025).